MIR613 (microRNA 613)
Synonyms: hsa-mir-613; MIRN613
Gene: MicroRNA gene on chromosome 12 (12,764,649 to 12,764,743, forward strand). Ensembl gene ENSG00000207983.
Diseases named in the same sentence as MIR613 in open-access papers:
MIR613 is named in the same sentence as 3 diseases in open-access papers, as found by Europe PMC text mining. Sharing a sentence is not in itself a finding about the gene and the disease. The quoted sentences say what the papers report.
glioma (1 paper, 2021). A benign or malignant brain and spinal cord tumor that arises from glial cells (astrocytes, oligodendrocytes, ependymal cells). "On the other hand, MIR613 was reported to act as a tumor suppressor, inhibiting glioma progression, while we found it up-regulated in the majority of the CNS tumors." (PMID 34204289, 2021).
MIR613 also shares sentences with these, for which no sentence is quoted: CNS tumors (1 paper); tumor (1).